KRAS (KRas proto-oncogene, GTPase)
Diseases named in the same sentence as KRAS in open-access papers (continued):
Sharing a sentence is not in itself a finding about the gene and the disease.
pancreatic cancer (continued). "The knockdown of TRIM37 in mouse pancreatic cancer cell line Pan18 and human pancreatic cancer cell lines, PANC-1 with KRAS mutation and BxPC-3 with wild-type KRAS, resulted in a significant reduction in the viability of pancreatic cancer cells." (PMID 35163097, 2022). "In pancreatic cancer, the ablation of the oncogenic drivers mutant KRAS and c-MYC induces a dormant state, allowing the survival of a few residual cancer cells that rely on autocrine IGF1/AKT as an adaptive mechanism." (PMID 35158815, 2022). "RPL36 was reported as a tumor suppressor to restrain KRAS-induced pancreatic cancer, and was a promising prognostic marker in hepatocellular carcinoma." (PMID 35145966, 2022). "Through a multiplex analysis approach, we explored that MYEOV has a positively correlated expression relationship with GPRC5A and KRAS, and further developed a molecular network of pancreatic cancer-related genes centered on MYEOV." (PMID 36358856, 2022). "NSC48160 inhibited the survival and growth of KRAS-driven pancreatic cancer cells CPFAC-1 (KRASG12V) and BxPC-3 (wild-type KRAS) by using MTT and colony-forming assays." (PMID 36291766, 2022). "About 20 kinds of KRAS-mutant pancreatic cancer cell lines were defined into either sensitive or resistant group, according to the median half-maximal inhibitory concentration (IC50) values of each MEKi in these cell lines." (PMID 35806187, 2022). "Accordingly, inhibition of glutathione biosynthesis has been harnessed as a therapeutic strategy in various preclinical models, including KRAS-driven pancreatic cancer and non-small cell lung cancer." (PMID 33594044, 2021). "Recently, researchers found that KRAS activation (90% of pancreatic cancers) leads to miR-489, which exerts control over the ECM." (PMID 33466892, 2021). "Recently, global metabolic reprogramming has been identified in patients with pancreatic cancer and oncogenic KRAS mouse models." (PMID 34064761, 2021). "The KRAS-targeting LNPK15 showed strong antitumor efficacy in tumor xenograft mice of MIA PaCa-2 pancreatic cancer although the in vitro knock down activity of lipid-based nanoparticle was rather weak compared to its effect in tumors." (PMID 34683931, 2021). "Upregulated KRAS promotes Lin28B nuclear translocation by PKCβ, but nuclear Lin28B further represses the production of let‐7, forming a KRAS/Lin28B/let‐7 loop in pancreatic cancer." (PMID 33107691, 2021). "Nevertheless, the genetic evidence is in line with our pharmacological results and confirms the synergy of PLK1 and FGFR inhibition in KRAS‐mutant lung and pancreatic cancer cells." (PMID 34369083, 2021). "In search of a molecular classifier for pancreatic cancers vulnerable to MAPK pathway blockade via MEK inhibition which is not dependent on a complex gene expression signature, our prior work identified the KRAS mutational isoform G12R as a candidate." (PMID 33405090, 2021). "Experiments with two KRAS G12C inhibition‐sensitive CDX models Mia PaCa‐2 (Pancreatic cancer) and NCI‐H358 (NSCLC) were used to evaluate the potential therapeutic utility of the AMG510‐IN10018 combination." (PMID 34151545, 2021). "Oncogenic KRAS mounts transcriptional responses that program the growth-promoting phenotype that characterizes pancreatic cancer initiation." (PMID 34249932, 2021). "Given the central role of KRAS in the initiation, growth, and progression of pancreatic cancer, it is imperative to target this oncogene." (PMID 38107772, 2021).
pancreatic cancer (continued). "Although functional studies of GNAS mutations in IMA have not been reported, codon 201 GNAS mutants function as oncogenes in KRAS-driven GEMMs of pancreatic cancer, which expresses some of the same foregut markers as IMA." (PMID 33821796, 2021). "have investigated the antitumor immune response of KRAS in pancreatic cancer using premalignant and PDAC cell lines, as well as orthotopic mice." (PMID 34781949, 2021). "Studies have also shown that NR5A2 cooperates with mutant KRAS to promote pancreatic cancer progression." (PMID 33850096, 2021). "In the specific context of pancreatic cancer, a reassessment of small molecule inhibitors of downstream effectors of KRAS in the context of our chemically engineered vulnerability is therefore warranted based upon forcing interactome hyperconnectivity states." (PMID 34824367, 2021). "Further studies on EVs as therapy delivery system are also needed, as EVs containing siRNA/shRNA against oncogenic KRAS suppressed cancer and increased overall survival in multiple mouse models of pancreatic cancer." (PMID 33995103, 2021). "SOX9 has been identified as a key downstream effector of KRAS, which promotes acinar to ductal metaplasia in early pancreatic cancer and accelerates malignancy." (PMID 33918004, 2021). "Three KRAS-dependent pancreatic cancer cell lines (HPAFII, MIA PaCa-2, PANC-1) were subjected to TOFA treatment." (PMID 34399819, 2021). "miRNA 216b was also downregulated in pancreatic cancer tissue and appeared to be related with the inhibition of pancreatic cancer cells proliferation as well as a KRAS-silencing induced apoptosis." (PMID 34470640, 2021). "The growth of certain pancreatic cancers is KRas-dependent and can be suppressed by GSK-3 inhibitors, documenting a link between KRas and GSK-3." (PMID 33917370, 2021). "Clinical data reported that KRAS and MYC oncogene signaling causes the suppression of type I IFN responses in pancreatic cancer cases." (PMID 34858438, 2021). "We observed mutant KRAS fragments in 9 of 17 (52.9%) late-stage pancreatic cancer samples vs. 7 of 20 (35%) control samples after collectively targeting 7 different KRAS alterations in the cfDNA." (PMID 33420235, 2021). "In this study, we demonstrated that BCL10 inhibition can result in differential cell cycle arrest in the two different pancreatic cancer cell lines: mutant KRAS cell lines (G2/M arrest) and wild-type KRAS cell lines (G1 arrest)." (PMID 34412631, 2021). "A clinical trial has tested cobimetinib in combination with gemcitabine to treat patients harbouring KRAS G12R mutant pancreatic tumours with two previously failed standard chemotherapeutic treatments." (PMID 33546207, 2021). "The newly produced lipids are used to construct membranes, ensuring survival and proliferation of the KRAS-driven pancreatic cancer cells." (PMID 34064761, 2021). "The KC and KPC mice are excellent research tools to initiate the sporadic formation of pancreatic tumors, but these models are less suitable to investigate the continued significance of KRAS in tumor maintenance and progression." (PMID 34491463, 2021). "The clinical trials using small molecule inhibitors targeting KRAS, resulted in promising anti-tumor effect for KRAS-mediated subtypes in pancreatic cancer." (PMID 34503185, 2021). "Commisso and colleagues have revealed oncogenic KRAS-mediated macropinocytosis as an entry route for extracellular albumin in 2D pancreatic cancer cell lines." (PMID 34112916, 2021). "These trials include binimetinib and HCQ in pancreatic and NSCLC, and trametinib and HCQ in KRAS mutant biliary tract carcinoma and pancreatic cancer." (PMID 34830283, 2021).
pancreatic cancer (continued). "A recent study demonstrated that oncogenic mutant KRAS in pancreatic cancer facilitated LD utilization via suppressing the expression and phosphorylation of HSL, thereby fueling cancer cell invasion." (PMID 34219130, 2021). "Taken together, our data identified CUX1 as an important enhancer of KRAS-induced tumor development in pancreatic cancer, acting synergistically with oncogenic KRAS by inducing several upstream and downstream effectors such as ADAM17 and MOS." (PMID 34070180, 2021). "The authors performed a pyrosequencing assay for KRAS (codon 12) mutations and immunohistochemistry for MUC1/MUC2, and compared the histological diagnosis of the initial tumor and the remnant pancreatic cancer in the resected group." (PMID 33805716, 2021). "We identified p110 CUX1 as major driver of pancreatic cancer formation in the context of mutant KRAS." (PMID 34070180, 2021). "Our data suggest a synergistic combination therapy for KRAS‐mutant lung and pancreatic cancer, which is also worthwhile to be tested in other KRAS‐driven malignancies." (PMID 34369083, 2021). "In an inducible KRASG12D pancreatic cancer mouse model, the amplification and overexpression of the transcriptional coactivator Yap1 has been demonstrated to be a potential KRAS independent bypass mechanism." (PMID 33777798, 2021). "This provides data to advance our understanding of the repertoire of epigenomic regulators that support the function of oncogenes (e.g., KRAS) so as to give rise to the pancreatic cancer phenotype." (PMID 34249932, 2021). "KRAS mutation, being the major driver in PDAC due to its presence in 90–95% of all pancreatic cancer samples, plays a central role to the KRAS pathway in pancreatic cancer development, and is therefore an ideal target for the management of PDAC." (PMID 34064761, 2021). "Notably, our GSEA analysis data showed that KLK8 overexpression might also lead to the activation of EMT (epithelial-mesenchymal transition), glycolysis and KRAS signaling pathway, which have been implicated in the pathogenesis and progression of pancreatic cancers." (PMID 34395235, 2021). "Genetic driving factors, including KRAS and several others, have been identified in pancreatic cancer." (PMID 34615858, 2021). "As a bona fide oncogenic driver of pancreatic cancer, the mechanism by which mutant KRAS counteracts the oncogenic stress that it induces is critically important for the progression of precursor lesions." (PMID 33983114, 2021). "The largest challenge with the genetic aberrations of pancreatic cancer is that the KRAS oncogene has been ‘undruggable’ using the now conventional treatment approach of targeted chemical inhibitors." (PMID 34683931, 2021). "In KRAS driven pancreatic cancer models, inhibiting JAK1/2 and TBK1 with momelotinib showed preclinical efficacy in vitro and in vivo." (PMID 33777798, 2021). "Level of mutant KRAS EVs in plasma even correlated with response to therapy and tumor burden with pancreatic cancer." (PMID 33995103, 2021). "GSTP is a well-known regulator of RAS signaling pathway proteins and it is extensively over-expressed in various types of cancer, especially KRAS mutant cancers including lung, colorectal and pancreatic cancer." (PMID 34371702, 2021). "ER stress is also involved in artesunate-induced ferroptosis in KRas mutant pancreatic cancer cells (PaTU8988 and AsPC-1) and in AsPC-1 xenografted BALB/c nude mice." (PMID 33467668, 2021). "KRAS is the most frequently mutated RAS family member (75% of RAS mutations), including high incidence of mutations in lung, colon, and pancreatic cancers, three of the top four causes of cancer-related death." (PMID 33924994, 2021).
pancreatic cancer (continued). "Remarkably, the deletion of IKK2/β in the pancreata of mice expressing mutant KRAS was sufficient to block the development of PanIN lesions and pancreatic tumors." (PMID 34491463, 2021). "These prompted us to study the involvement of ARL4C, as a KRAS downstream molecule, in aggressiveness of pancreatic cancer, and IQ-domain GTPase-activation protein 1 (IQGAP1) was identified as a binding protein of ARL4C." (PMID 34590580, 2021). "Studies have shown that Yes-associated protein (YAP), the major nuclear effector in the Hippo signaling pathway, enables the bypass of oncogenic KRAS addiction in pancreatic cancer." (PMID 34512171, 2021). "The increase in glucose uptake supports KRAS to promote synthesis of proteins, nucleic acids and fatty acids that are essential for pancreatic cancer cell proliferation." (PMID 34781949, 2021). "Although the EGFR inhibitor erlotinib has been given the green light from the FDA to treat pancreatic cancer for over 10-year period, detailed downstream signaling targets, e.g., KRAS, are promising and require further study." (PMID 34360896, 2021). "Selumetinib is also being tested for patients with locally advanced/metastatic KRAS G12R mutant pancreatic cancer (NCT03040986)." (PMID 33546207, 2021). "In this study, we found that Lin28B was significantly more highly expressed in pancreatic cancer tissues than in the pancreatic cancer adjacent tissues, and showed that KRAS promoted the nuclear translocation of Lin28B by protein kinase C (PKCβ)." (PMID 33107691, 2021). "We present a 34-year-old young man with ALK rearrangement-positive and KRAS-wild pancreatic cancer who had a remarkable response to crizotinib after resistance to prior chemotherapy and re-response to alectinib after brain metastases developed." (PMID 34568053, 2021). "Recently, we involved the carbohydrate-binding protein Galectin-3 (Gal-3) as a druggable target for KRAS-mutant-addicted lung and pancreatic cancers." (PMID 34112916, 2021). "Using TCGA pancreatic cancer data, we found that between KRAS wild-type and mutants, there was a significant difference in the HIST2H2AA3 expression level (p = 0.001), but not in that of LUZP6 (p = 0.5) or HLA-DRA (p = 0.06)." (PMID 34073722, 2021). "In pancreatic cancer cells KRAS activates Hedgehog pathway, which is involved in the generation and maintenance of the typical dense tumor stroma." (PMID 33777798, 2021). "Similar to the mutant KRAS models, the survival of pancreatic cancer cells at primary and metastatic sites was dependent on the perpetual expression of c-MYC." (PMID 34491463, 2021). "In KRAS mutant lung and pancreatic cancer, mutant KRAS transcriptionally activates NRF2, a principal modulator of cellular redox, resulting in a reduced intracellular ROS level and leading to increased glutamine dependency." (PMID 34680229, 2021). "In pancreatic cancers the diagnosis made by the combined KRAS mutations in ctDNA and CA19-9 is more sensitive than the KRAS mutation in ctDNA alone." (PMID 33593396, 2021). "In the present study, we demonstrate that KRAS‐mutant lung and pancreatic cancers are highly sensitive to concomitant inhibition of FGFR1 and PLK1." (PMID 34369083, 2021). "It has been demonstrated that in pancreatic cancer cell lines with wild-type KRAS, RACK1 and syndecan-2 are interacting." (PMID 33669066, 2021). "YAP has also shown to be a critical oncogenic KRAS effector and a promising therapeutic target for pancreatic cancer." (PMID 33946266, 2021). "Attempts to treat pancreatic cancer using drugs that reduce the activity of KRAS have so far failed." (PMID 34590580, 2021).
pancreatic cancer (continued). "The IGF1/IGF-1R signaling axis was also shown to promote the survival of dormant pancreatic cancer cells after oncogenic KRAS or MYC ablation in pancreatic cancer cells." (PMID 33807785, 2021). "Our research group and others have demonstrated that the lipid kinase PI3Kα drives the initiation of pancreatic cancer downstream of oncogenic KRAS." (PMID 34033220, 2021). "In pancreatic cancer, a mechanical imbalance following the oncogenic KRAS expression similar to the one studied here drives the pathological morphing of the pancreatic duct." (PMID 34644109, 2021). "Earlier studies in genetic mouse models of KRAS mutant pancreatic cancer showed the potential of using DFMO as a chemoprevention agent." (PMID 34947972, 2021). "Kirsten rat sarcoma viral oncogene homolog (KRAS)-driven pancreatic cancer is very lethal, with a five-year survival rate of <9%, irrespective of therapeutic advances." (PMID 34064761, 2021). "Kirsten rat sarcoma 2 viral oncogene homolog (KRAS) plays an important role in the metastasis of pancreatic cancer via affecting multiple cellular events such as apoptosis." (PMID 33435156, 2021). "In fact, ROS have been shown to be critical for mutant oncogenic KRAS-driven transformation and pancreatic tumor growth." (PMID 33546421, 2021). "KRAS G12 mutations (DII, PII) were also detected in 10 out of 12 patients of the pancreatic cancer cohort, in which it has diagnostic implications as it can be used to differentiate it from chronic pancreatitis." (PMID 33947144, 2021). "In in vivo tumor models (including colorectal and pancreatic cancers), this molecule led to tumor regression through a dose-dependent inhibition of the KRAS signalling pathway." (PMID 34944952, 2021). "For example, HFD can promote the development of pancreatic tumors by over-activating oncogenic KRAS to induce aerobic glycolysis." (PMID 33897888, 2021). "It has been described as an activator of KRAS and glypican-1 in pancreatic cancer and, very recently, it was reported in relation to acinar cell-derived tumorigenesis." (PMID 33762742, 2021). "Mutated KRAS increases phosphorylation of ERK, indicating that RAS-MAPK signaling contributes significantly to pancreatic cancer progression." (PMID 34439095, 2021). "Expression of the lipogenic enzymes is regulated by the transcription factor sterol response element-binding protein 1 (SREBP1) controlled by the PI3K/AKT signaling pathway, which is upregulated by oncogenic KRAS in pancreatic cancer." (PMID 34064761, 2021). "Treatment with MEK inhibitors have been shown to increase autophagy in pancreatic cancer with mutant KRAS genes." (PMID 33917370, 2021). "Oncogenic KRAS signaling drives several effector cascades that contribute not only to the malignant behavior of pancreatic cancer cells but also formation of the fibro-inflammatory microenvironment." (PMID 34771644, 2021). "Here, we reported, for the first time, that combined treatment with FGFR1 and PLK1 inhibitors evokes synergistic cytotoxic activity in KRAS‐mutant lung and pancreatic cancer models in vitro and in vivo." (PMID 34369083, 2021). "In vitro and in vivo, knocking down or knocking out RAGE delays the growth of oncogenic KRAS-driven pancreatic tumors and reverses drug resistance." (PMID 33918146, 2021). "Pre-clinical studies with AZD6244 have shown regression of tumors both in KRAS wild-type BxPC3 pancreatic tumor xenograft model, as well as in colorectal, pancreatic, non-small cell lung, hepatocellular, and melanoma human xenograft models." (PMID 34944853, 2021). "In pancreatic cancer KRAS is known to upregulate Raf-MEK-ERK and PI3K/Akt signaling pathways which promote cell growth and survival of pancreatic cancer cells." (PMID 38107772, 2021).